OPHN1 (oligophrenin 1)
Description:
Stimulates GTP hydrolysis of members of the Rho family. Its action on RHOA activity and signaling is implicated in growth and stabilization of dendritic spines, and therefore in synaptic function. Critical for the stabilization of AMPA receptors at postsynaptic sites. Critical for the regulation of synaptic vesicle endocytosis at presynaptic terminals. Required for the localization of NR1D1 to dendrites, can suppress its repressor activity and protect it from proteasomal degradation (By similarity).
Synonyms: OPN1; ARHGAP41; MRX60; MRXSBL
Tractability: Antibody: the Human Protein Atlas places it where antibodies can reach. PROTAC: ubiquitination databases record sites on it; its protein half-life has been measured.
Gene: Protein-coding gene on chromosome X (67,949,349 to 68,434,120, reverse strand). Ensembl gene ENSG00000079482.
Subcellular location: Postsynapse; Presynapse; Cell projection, axon; Cell projection, dendritic spine; Cell projection, dendrite; Cytoplasm
Subcellular location (Human Protein Atlas): Nucleoplasm; Plasma membrane
Pathways (Reactome):
Signal Transduction: CDC42 GTPase cycle; RAC1 GTPase cycle; RAC2 GTPase cycle; RAC3 GTPase cycle; RHOA GTPase cycle; RHOB GTPase cycle; RHOC GTPase cycle; RHOG GTPase cycle; RHOJ GTPase cycle; RHOQ GTPase cycle
Gene Ontology:
Molecular function: phospholipid binding; GTPase activator activity; actin binding; ionotropic glutamate receptor binding
Biological process: cell junction assembly; cell morphogenesis involved in neuron differentiation; cerebellar granule cell differentiation; cerebral cortex neuron differentiation; establishment of epithelial cell apical/basal polarity; neuron differentiation; neuron projection development; regulation of postsynaptic neurotransmitter receptor internalization; regulation of Rho protein signal transduction; actin cytoskeleton organization; axon guidance; negative regulation of proteasomal protein catabolic process; nervous system development; regulation of endocytosis; regulation of synaptic transmission, glutamatergic; signal transduction; substrate-dependent cell migration, cell extension; synaptic vesicle endocytosis; maintenance of postsynaptic specialization structure; regulation of synaptic vesicle endocytosis
Cellular component: glutamatergic synapse; actin cytoskeleton; cytoplasm; dendritic spine; postsynapse; presynapse; terminal bouton; axon; dendrite; synapse
Gene-disease validity (ClinGen):
ClinGen rates the evidence that OPHN1 causes each of these diseases.
X-linked intellectual disability-cerebellar hypoplasia syndrome (X-linked): Definitive.
Homologues: Orthologues: macaque OPHN1 (99% identical), pig OPHN1 (95% identical), guinea pig OPHN1 (94% identical), rabbit OPHN1 (93% identical), chimpanzee OPHN1 (92% identical), mouse Ophn1 (92% identical), rat Ophn1 (92% identical), tropical clawed frog ophn1 (71% identical), zebrafish ophn1 (63% identical), Drosophila melanogaster Graf (35% identical), Caenorhabditis elegans T04C9.1 (33% identical). Paralogues in human: ARHGAP42 (52% identical), ARHGAP26 (44% identical), ARHGAP10 (43% identical).
Diseases named in the same sentence as OPHN1 in open-access papers:
OPHN1 is named in the same sentence as 51 diseases in open-access papers, as found by Europe PMC text mining. Sharing a sentence is not in itself a finding about the gene and the disease. The quoted sentences say what the papers report.
Intellectual disability (20 papers, 2010 to 2025). "In family EP02, one affected individual carried a heterozygous class III variant in OPHN1 (c.1490G > A, p.(Arg497Gln)), related to syndromic X‐linked intellectual disability with epilepsy." (PMID 39400946, 2025). "For children presenting with seizures, intellectual disability, and visual impairment accompanied by cerebellar hypoplasia, it is recommended to include OPHN1 gene mutation screening as part of the diagnostic process." (PMID 38956616, 2024). "To date, over 100 cases of intellectual developmental delay linked to mutations in the OPHN1 gene have been reported, encompassing more than 20 distinct mutation variants known to contribute to conditions such as intellectual disability and autism." (PMID 38956616, 2024). "Loss-of-function mutations in the human oligophrenin-1 (OPHN1) gene cause intellectual disability, a prevailing neurodevelopmental condition." (PMID 33892766, 2021). "XLID, characterized by brain anomalies, namely cerebellar hypoplasia, specific facial features, and intellectual disability, is produced by different mutations in the OPHN1 gene." (PMID 32872024, 2020). "Two of the top 10 X chromosome SNPs were located in OPHN1, a gene previously associated with X-linked mental retardation." (PMID 28196072, 2017). "Additional ROHs at Xq11.1-q12 and Xp11.22-p11.21 included genes (e.g., OPHN1) when defective are implicated in the development of intellectual disabilities." (PMID 25400949, 2014). "Moreover, a form of intellectual disability is due to mutations of the OPHN1 (Oligophrenin-1) gene, which encodes for a Rho-GTPase-activating protein promoting GTP hydrolysis of Rho subfamily members, thus controlling the contractile properties of the actin/myosin complex." (PMID 26760504, 2016). "Further genes of the Rho GTPase family, like OPHN1, ARHGEF6 and PAK3, have been implicated in non-syndromic intellectual disability and play a role in spine morphology and synaptic plasticity." (PMID 29685133, 2018). "We selected known synaptic RhoGTPase regulatory proteins, β-PIX, a GEF, and OLIGOPHRENIN-1, a GAP protein that is mutated in non-syndromic mental retardation." (PMID 28114311, 2017). "OPHN1 was first identified in a female patient showing mild intellectual disability and carrying a (X;12)(q11;q15) translocation." (PMID 24637888, 2014). "In the present study, we investigate the role of oligophrenin-1 in neuronal network activity, particularly spontaneous and KA-induced gamma oscillations using the Ophn1 mouse model of intellectual disability." (PMID 24800744, 2014). "In the microarray results the probe for oligophrenin-1, a gene known for its involvement in mental retardation, showed a decreased hybridization signal." (PMID 20602808, 2010). "Multiple post-transcriptional events involving the OPHN1 protein, along with editing/splicing of mutant OPHN1 protein, may play a significant role in the pathogenesis of intellectual disability." (PMID 38956616, 2024). "Additionally, evidence about fasudil's effect on improving novel object recognition deficits in MK-801-treated mice and rescue working memory deficits and object recognition tasks in an Oligophrenin-1 mouse model of intellectual disability also exists." (PMID 39534317, 2024). "Interestingly, similar phenotypes of altered social behaviors and reduced behavioral lateralization were previously reported in other mouse models of intellectual disability such as, for example, Ophn1, Gdi1, Fmr1, motopsin, and Pten mutants." (PMID 24073232, 2013).
X-linked intellectual disability (6 papers, 2013 to 2024). An X-linked intellectual deficiency in which not enough information is known, reported or published to indicate whether a gene causes non-syndromic or syndromic presentations. "It was confirmed that OPHN1: c.1025 + 1G > A is the pathogenic cause of X-linked intellectual disabilities in the child, with clinical phenotypes including developmental delay and seizures." (PMID 38956616, 2024). "The oligophrenin-1 (OPHN1) gene, localized on the X chromosome, is a Rho-GTPase activating protein that is related to syndromic X-linked intellectual disability (XLID)." (PMID 32872024, 2020). "The OPHN1 geneencodes the Rho GTPase-activating protein associated with X-linked intellectual disabilities and cerebellar hypoplasia." (PMID 25400949, 2014). "For example, RAC1 partners with oligophrenin-1 and synaptojanin which have been linked to X-linked intellectual disability and Down’s syndrome, respectively." (PMID 23803181, 2013). "Oligophrenin-1 (OPHN1) is a Rho-GTPase-activating protein (RhoGAP), whose mutations are associated with X-linked intellectual disability (XLID)." (PMID 35563851, 2022). "Oligophrenin-1 is mutated in X-linked intellectual disability with or without cerebellar hypoplasia." (PMID 30534410, 2018).
Cerebellar hypoplasia (4 papers, 2011 to 2024). Cerebellar hypoplasia is a descriptive term implying a cerebellum with a reduced volume, but a normal shape and is stable over time. "Variations in this gene have been implicated in OPHN1-related X-linked cognitive disability with cerebellar hypoplasia and distinctive facial dysmorphisms." (PMID 38956616, 2024). "The best characterized forms are X-linked syndromes with associated cerebellar hypoplasia due to OPHN1 or CASK gene mutations." (PMID 21569638, 2011). "Interestingly, OPHN1 is highly expressed in cerebellum compared to the brain and mutations in this gene are associated with cerebellar hypoplasia." (PMID 24637888, 2014).
Cognitive impairment (4 papers, 2014 to 2021). Abnormal cognition is characterized by deficits in thinking, reasoning, or remembering. "We also found that loss of Graf causes a specific defect in olfactory long-term memory, possibly paralleling cognitive impairments caused by OPHN1 loss in humans." (PMID 33892766, 2021). "ISRIB has also been used to address expression of OPHN1 as a translational downstream target of p-eIF2α that is associated with mGluR-LTD-linked cognitive disorders." (PMID 30024379, 2018). "To further understand the role of oligophrenin-1 in cognitive deficits, we examined synchronous neuronal activity in the gamma frequency band." (PMID 24800744, 2014). "Another recent study demonstrated that Ophn1-/y mice display cognitive impairment in Y-maze spatial working memory test with high occurrence of perseverative behaviors, which suggests poor behavioral flexibility in Ophn1-/y mice." (PMID 32244264, 2020).
prostate carcinoma (3 papers, 2020 to 2024). A carcinoma that arises from epithelial cells of the prostate gland. "OPHN1 overexpression was observed in prostate cancer (PCa) after androgen deprivation therapy, which promoted PCa progression and cell survival." (PMID 38498903, 2024). "We found lnc-OPHN1-5, which lies close to the androgen receptor (AR) gene on chromosome X, increased prostate cancer (PCa) Enzalutamide (Enz) sensitivity via decreasing AR protein expression and associated activity." (PMID 34545067, 2021). "The positive of oligophrenin-1 was significantly correlated with a high Gleason score in prostate cancer." (PMID 32190687, 2020).
schizophrenia (3 papers, 2013 to 2022). A major psychotic disorder characterized by abnormalities in the perception or expression of reality. "To date, the mutations detected in the OPHN1 gene have been described in subjects with neurodevelopmental diseases such as ID, ataxia, epilepsy, seizure, and schizophrenia." (PMID 32872024, 2020).
Ataxia (2 papers, 2020 to 2025). Ataxia refers to impaired coordination of voluntary muscle movement. "Pathogenic variants in OPHN1 cause X‐linked intellectual disability with ataxia, seizures, strabismus, but also cerebellar hypoplasia and ventriculomegaly (#OMIM 300486), neither of which have been seen on the CT‐scan in our patient." (PMID 39400946, 2025).
Strabismus (2 papers, 2011 to 2025). A misalignment of the eyes so that the visual axes deviate from bifoveal fixation. "Another deletion comprising exon 19 of the OPHN1 gene, was identified in a family with five affected males showing moderate to severe mental retardation, infantile-onset epilepsy, hypotonia, strabismus and ataxia." (PMID 21569638, 2011).
allergic asthma (1 paper, 2015). A asthma with a basis in a pathological type I hypersensitivity reaction. "Furthermore, the upregulated genes (PDPK1, EZR, MYO6, CDC42BPA, OPHN1, ARF6 and WASL) identified in the present study that were enriched in the actin filament-based process require further study in order to determine whether they may be used as potential biomarkers of allergic asthma." (PMID 25633562, 2015).
Asperger syndrome (1 paper, 2014). "Of these, OPHN1, IGBP1, DLG3, NLGN3, and ZDHHC15 are associated with mental retardation or Asperger syndrome phenotypes." (PMID 24778889, 2014).
astrocytomas (1 paper, 2014). "We found that, in cancer cells (astrocytomas) and brain tissues, OPHN1 is alternatively spliced in this region." (PMID 24637888, 2014). "Of note, previous studies have already reported that OPHN1 is expressed in astrocytoma/GBM tumors." (PMID 24637888, 2014). "Moreover, we reported that editing and expression of OPHN1 increase when ADAR2 is expressed in astrocytoma cell lines (U118 and U87)." (PMID 24637888, 2014).
baldness (1 paper, 2017). "The top X chromosome gene-based findings included the androgen receptor (AR), which has been well established as a baldness associated gene, along with its upstream (EDA2R) and downstream (OPHN1) genes." (PMID 28196072, 2017).
craniofrontonasal syndrome (1 paper, 2017). "Furthermore, a contiguous deletion of a region containing EFNB1, ‘Oligophrenin 1’ (OPHN1), PJA1 and EDA was reported in patients with craniofrontonasal syndrome." (PMID 28877219, 2017).
cryptorchidism (1 paper, 2020). The failure of one or both testes of a male fetus to descend from the abdomen into the scrotum during the late part of pregnancy. "Several authors reported cases with cryptorchidism, micropenis, hypoplastic scrotum connected with the OPHN1 gene, but in our study, none of our subjects presents abnormal external genitalia." (PMID 32872024, 2020).
viral infection (1 paper, 2016). "Furthermore, we confirmed by WB analysis the effect of viral infection with pLKO-shRNF10 on protein levels of some of the RNF10 target genes, such as Ophn1, ArhGap4 and ArhGef6." (PMID 26977767, 2016).
X-linked mental retardation syndrome (1 paper, 2016). "Parent number 5 is the mother of a 20-year-old with a mutation in OPHN1, resulting in an X-linked mental retardation syndrome." (PMID 27082877, 2016).
tumor (3 papers, 2021 to 2026). "Consistently, the in vivo mice model confirmed that knocking down lnc-OPHN1-5 expression in tumors significantly increased the tumor formation rate and AR protein expression compared with the control group." (PMID 34545067, 2021). "We further examined whether the lnc-OPHN1-5 could influence the Enz treatment sensitivity or tumor growth in the in vivo mice model." (PMID 34545067, 2021). "This analysis revealed associations with multiple proteins, including SMAD3, RNF14, PPM1A, and OPHN1, implicating PCDH1 in signaling cascades relevant to tumor progression and stemness regulation." (PMID 41602375, 2026).
neurodevelopmental disorder (2 papers, 2017 to 2024). A behavioral and cognitive disorder with onset during the developmental period that involves impaired or aberrant development of intellectual, motor, or social functions. "Numerous clinical studies have documented the association of the OPHN1 gene with neurodevelopmental disorders." (PMID 38956616, 2024). "Collectively, functional defects of NR1D1 as well as Oligophrenin-1 are likely to relate to the pathophysiology of neurodevelopmental disorders such as ASD and ID." (PMID 28262759, 2017).
neurological disorders (2 papers, 2017 to 2022). "Most importantly, several DEGs such as CX3CL1, SEMA3F, OPHN1, POLA2, MCM10 and POLD3 were found to be associated with neuronal/brain process and genome stability, that is known to be relevant during neurological disorders." (PMID 36267332, 2022). "We identified four genes that had already been associated with neurological disorders (AFF2, ALG13, OPHN1, and RBM10)." (PMID 28769055, 2017).
OPHN1 also shares sentences with these, for which no sentence is quoted: autism (2 papers); behavioral disorder (2); developmental delay (2); epilepsy (2); autism spectrum disorder (1); autosomal dominant mental retardation-29 (1); cancer (1); cognitive disorder (1); Dandy-Walker malformation (1); depression (1); Down syndrome (1); emphysema (1); genetic disorder (1); Hydrocephalus (1); Hypertelorism (1); hypoaldosteronism (1); Krabbe disease (1); learning disabilities (1); leukodystrophy (1); McArdle disease (1); metabolic dysfunction-associated steatohepatitis (1); Micrognathia (1); Micropenis (1); muscular dystrophy (1); neuroblastoma (1); Nystagmus (1); Schinzel-Giedion syndrome (1); Seizure (1); Turner syndrome (1); Ventriculomegaly (1).
A further 2 diseases each share a sentence with OPHN1 in 1 paper.